HPSE (heparanase)
Diseases named in the same sentence as HPSE in open-access papers (continued):
Sharing a sentence is not in itself a finding about the gene and the disease.
breast carcinoma (continued). "Interestingly, estrogen stimulation of breast cancer cells at low concentrations induced higher expression levels of heparanase than high concentrations of estrogen." (PMID 34681753, 2021). "Our study proved the correlation between HPSE expression and tumor-infiltrating immune cells, and supported the intimate correlation between HPSE expression and immune cell infiltration in bladder and breast cancer." (PMID 34461608, 2021). "In addition, while increased heparanase activity was reported in lapatinib-resistant HER2 and EGFR-positive breast cancer cells, heparanase inhibition was found to re-sensitize these cells to lapatinib." (PMID 35118073, 2021). "Finally, we showed that heparanase increased cell survival following 5-FU treatment in MCF7 human breast cancer cells via the anti-apoptotic pathway." (PMID 34050190, 2021). "Together, our results show that HPSE may serve as a novel biomarker for immune infiltration and prognosis in breast cancer." (PMID 34461608, 2021). "Taken together, our results demonstrate the importance of heparanase in increasing cell viability of breast cancer and may help identify patients that can benefit from adjuvant chemotherapy in ER+ breast cancer." (PMID 34050190, 2021). "We next assessed whether heparanase was correlated with survival in breast cancer patients for whom relapse data were available." (PMID 34050190, 2021). "We now evaluated heparanase protein and gene-expression status and investigated its impact on disease-free survival in order to gain better insight into the role of heparanase in ER-positive (ER+) breast cancer prognosis and to clarify its role in cell survival following chemotherapy." (PMID 34050190, 2021). "Heparan sulfate degradation was increased in the presence of overexpressed heparanase induced by tamoxifen treatment in ER positive breast cancer, which may be able to promote tumor invasion and therefore confer tamoxifen resistance." (PMID 33324567, 2020). "Several studies have provided evidence that heparanase plays a major role in progression of a variety of cancers including liver cancer, sarcomas, ovarian cancer, breast cancer, and colon cancer." (PMID 32984308, 2020). "The attempt at mimicking the structure of HS has seen the development of glycopolymers with well-defined sulfation patterns and the ability to optimize disaccharide length for peak heparanase inhibition, which reduced metastasis of breast cancer in a rodent model." (PMID 32010611, 2019). "For example, heparanase was shown to induce the clustering of breast cancer cells in a manner reminiscent of circulating tumor cells, and knockdown of heparanase inhibited the formation of these cancer cell clusters and suppressed breast cancer metastasis." (PMID 31850210, 2019). "In addition, heparanase inhibitors were found to efficiently attenuate the tumorigenic capacity of breast carcinoma cells, altogether implying that heparanase plays a decisive role in breast cancer." (PMID 29464068, 2018). "Similarly, overexpression of heparanase promotes, while anti-heparanase siRNA decreases the growth, angiogenesis, and metastasis of breast carcinoma cells." (PMID 29464068, 2018). "Thus, heparanase levels can assist in the diagnosis, necessity, and type of treatment in early stage breast cancer." (PMID 29464068, 2018). "Besides the MMPs, the enzymes such as LOXL2, LOXL4, procollagen lysyl hydroxylase-2, and heparanase also regulate breast cancer progression." (PMID 29983921, 2018). "Thus, heparanase levels can assist in the diagnosis and in determining the necessity and type of treatment in early stage breast cancer." (PMID 29464068, 2018). "In the present study we show that the interplay between heparanase and insulin signaling may foster breast tumorigenesis, mechanistically linking the enzyme into the breast cancer-promoting action of metabolic disorders." (PMID 28038446, 2017). "Estrogen signaling has been previously shown to induce heparanase in breast carcinoma." (PMID 28038446, 2017).
breast carcinoma (continued). "We found that HPSE was overexpressed in breast cancer tissue compared to normal breast tissue." (PMID 28388549, 2017). "To test this hypothesis, we first incubated ER-positive MCF-7 human breast carcinoma cells with insulin in the absence or presence of recombinant active heparanase enzyme." (PMID 28038446, 2017). "Interestingly, several Chinese herbal medicines that have been used as components of breast cancer treatment in a number of countries have shown anti-HPSE activity." (PMID 28388549, 2017). "Therefore, in this study, we analyzed studies and TCGA data of HPSE expression in breast cancer to evaluate its prognostic value." (PMID 28388549, 2017). "Here we present the evidence that activity of heparanase enzyme (the only known mammalian endoglycosidase that cleaves HS) leads to enhanced insulin signaling and activation of downstream tumor-promoting pathways in breast carcinoma cells." (PMID 28038446, 2017). "Moreover, several studies have demonstratedthat heparanase is up-regulated in all human sarcomas and carcinomas and it is detected at elevated levels in body fluids of breast cancer patients." (PMID 27322195, 2016). "Moreover, ERK inhibition was also observed when lapatinib resistant breast cancer cells were treated with Roneparstat, consistent with our previous finding that Roneparstat blocks heparanase-induced ERK signaling." (PMID 26624982, 2016). "Although little is known regarding the role of heparanase in drug resistance, it was recently reported that lapatinib-resistant breast cancer cell lines express high levels of heparanase and use of the heparanase inhibitor Roneparstat sensitized the drug resistant breast cancer cells to lapatinib." (PMID 26624982, 2016). "It had already been observed in previous studies from our laboratory that heparanase-1 and heparanase-2 isoforms were overexpressed in the blood (mononuclear cell fraction) of women with breast cancer, thereby suggesting that this tumor can possibly modulate the expression of both heparanases." (PMID 25351637, 2015). "It has been previously documented that MMPs and HPSE play essential roles in breast cancer." (PMID 26084486, 2015). "In addition, the serum heparanase levels of patients with metastatic breast cancer were significantly higher than primary breast cancer patients." (PMID 25105093, 2014). "Heparanase promotes tumor invasion and metastasis in several malignancies including breast cancer." (PMID 24632672, 2014). "In breast cancer, miR-1258 alterations were directly related to heparanase expression, a known prometastatic enzyme found in brain metastatic breast cancer cells that degrades heparan sulfate chains to affect the cytoskeleton and render cells more capable of crossing the BBB." (PMID 24921708, 2014). "Li Y and colleagues proved that downregulation of heparanase could suppress ER stress-induced invasion and migration of breast cancer cells." (PMID 25226618, 2014). "The preferential overexpression of heparanase has also been demonstrated in breast cancer." (PMID 24632672, 2014). "In the present study, we tested whether DNA methylation is involved in the differential regulation of heparanase during breast cancer progression." (PMID 24632672, 2014). "The methylation patterns of the heparanase gene in control and breast cancer with different stage." (PMID 24632672, 2014). "For in vitro systems, cell models demonstrated that silencing heparanase in breast cancer cells could decrease their invasion and adhesion." (PMID 24632672, 2014). "The role of heparanase and HS in breast cancer has been discussed comprehensively in a recent review but emerging data continues to identify heparanase as a prognostic marker for tumor progression in breast cancer." (PMID 25105093, 2014). "Moreover, this work reveals that Tamoxifen, a common drug used to treat breast cancer (ER+) patients, induces heparanase expression in MCF-7 and T47D cells." (PMID 23984412, 2013).
breast carcinoma (continued). "Also, lymphocytes derived from breast cancer patients affect healthy lymphocytes, turning them into tumor-inducing cells via heparanase expression." (PMID 23984412, 2013). "Several tumor types including breast cancers show aberrant modulation of several enzymes related to heparan sulfate (HS)/ heparin biosynthesis, as well as catabolic enzymes such as sulfatases and heparanase-1 (HPSE1)." (PMID 24083474, 2013). "For instance, as tumours become more aggressive, heparanase activity is enhanced in myeloma, lymphomas or breast cancer, increasing both the number of exosomes released and the amount of syndecan-1, VEGF and HGF molecules exposed on their surface, making them more available for detection." (PMID 24223259, 2013). "Moreover, the expression of miR-1258 in BM from breast cancer cells has been shown to suppress heparanase in vitro cell invasion and experimental BM." (PMID 22567347, 2011). "Thus, it is possible that the induction of heparanase expression by low levels of estrogen in healthy breast tissue may contribute to the initiation of breast cancer." (PMID 34681753, 2021). "Notably, HPSE expression significantly impacted prognosis in bladder and breast cancers." (PMID 34461608, 2021). "Hence, CDYL2b might regulate the migration, invasion, and metastasis of breast cancer through, at least partly, regulating HPSE, HLA-F, and SELL expression." (PMID 32373210, 2020). "In addition to this, it has recently been shown that overexpression of heparanase promotes the formation of cell clusters in MDA-MB-231 breast cancer cells, most likely by modulating the level of intercellular adhesion molecule 1 (ICAM-1) and phosphorylation status of downstream kinases." (PMID 32984308, 2020). "Indeed, chemically synthetic HS tetrasaccharides containing unsubstituted GlcN residues, GlcAβ1-4GlcNH3+ (6-O-sulfate)α1-4GlcAβ1-4GlcNH3+ (6-O-sulfate)(TD4-143-1), accumulated in lysosomes, inhibited heparanase activity, and suppressed invasion of breast cancer cells in vitro." (PMID 30413079, 2018). "Besides, although heparanase expression and its function in tumor invasion have been well studied, little is known about the epigenetic mechanism that governing the expression of heparanase transcription in breast cancer with different potentials of invasion and metastasis." (PMID 24632672, 2014). "Finally, clinical specimens with different invasive stage were tested to identify whether there is a correlation between DNA hypomethylation and heparanase overexpression during breast cancer progression." (PMID 24632672, 2014). "Analysis of the TCGA database showed that the expression of genes HPSE, PIK3AP1, SIGLEC7, LAIR1, and CTSL have positive correlations according to the breast cancer subtypes." (PMID 33053017, 2020). "We propose to conduct this study on both isoforms of heparanase, namely heparanase-1 (HPSE) and heparanase-2 (HPSE2), in the context of breast cancer." (PMID 33053017, 2020). "The immunocytochemistry analysis clearly demonstrated the increased expression of both isoforms of heparanase (HPSE and HPSE2) in T-lymphocytes exposed to the plasma of breast cancer patients or to MCF-7 cells." (PMID 30922347, 2019). "Breast cancer cells (MCF-7) and co-culture medium were able to upregulate both heparanase isoforms in circulating lymphocytes, mimicking the effect of plasma from breast cancer patients." (PMID 30922347, 2019). "We found that overexpression of heparanase in human tumor cells (i.e., Fadu pharyngeal carcinoma, MCF7 breast carcinoma) attenuated TGF‐β1‐stimulated Smad phosphorylation and led to a slower cell proliferation." (PMID 28286736, 2017). "Extensive studies have confirmed that heparanase, which participates in the degradation of the ECM, is overproduced in several types of tumor including breast cancer." (PMID 28505136, 2017).
breast carcinoma (continued). "Then heparanase expression profile of three different cell lines was investigated: one microvascular (HSk-MEC) and two mammary carcinoma cell lines (MDA-MB-231 and MCF-7)." (PMID 28486399, 2017). "Additional breast cancer cell lines and breast cancer tissue can be tested specifically for CXCL7 expression and effects on lymphangiogenesis, heparanase expression and invasion in the future." (PMID 20652010, 2010). "Heparanase and the lymphangiogenesis factors VEGF-C and VEGF-D are two important markers closely related to the metastasic capabilty of breast cancer." (PMID 20652010, 2010). "The abundance of obesity-associated ECM accessory proteins HA and endotrophin is associated with poor disease outcomes in pan-subtype analyses of breast cancer patients, while expression of heparanase, which regulates ECM at the cell surface, is predictive of poor prognosis in HR+ breast cancer." (PMID 40847127, 2025). "Although it is known that HPSE is overexpressed in breast cancer, it is not well understood precisely when during mammary tumour development this change occurs." (PMID 37297024, 2023). "HPSE was also suggested to play no significant role during the early stages of mammary tumour development, which had remained largely undefined." (PMID 37297024, 2023). "Based on the observations reported herein, it can be suggested that in the MMTV-PyMT model, a reduction in mammary tumour angiogenesis as a result of the lack of HPSE expression does not impact the overall tumour growth capacity." (PMID 37297024, 2023). "Together, these data suggest that HPSE does not play a role in promoting the progression of MMTV-PyMT mammary tumours early in their development." (PMID 37297024, 2023). "We have recently discovered an overexpression of heparanase and Sdc-1 in triple-negative inflammatory breast cancer, an aggressive form of breast cancer represented by the SUM-149 cell line employed in this study." (PMID 34066023, 2021). "Importantly, compound 4-MMI yielded a nearly fourfold inhibition of 4T1 breast carcinoma metastasis, comparable to the effect exerted by Roneparstat (=SST), a well-characterized heparin-like heparanase inhibitor." (PMID 34199150, 2021). "Although the role of heparanase in tumor progression and upregulation of its abundancy have been detected in breast cancer, the specific function of heparanase in the chemoresistance of breast cancer has not yet been explored." (PMID 34050190, 2021). "The increased HPSE expression correlated with poor prognosis and increased immune infiltration levels of B cells, CD8+ and CD4+ T cells, macrophages, neutrophils and dendritic cells in bladder and breast cancer." (PMID 34461608, 2021). "This is the case in breast cancer patients, where the primary lesion stained positive for heparanase in some cases while the metastasis stained negative, and vice versa." (PMID 31963505, 2020). "To further verify that CDYL2b affects the migratory and invasive potential of breast cancer cells through transcriptional repression of HPSE, HLA-F, and SELL, we conducted rescue experiments by restoring HPSE, HLA-F, and SELL expression in MDA-MB-231 and Hs578T cells stably expressing CDYL2b." (PMID 32373210, 2020). "In addition, ARG inhibited the metastasis of human breast cancer cells by reducing the activity of MMP2, MMP9, and heparanase protein." (PMID 33015162, 2020). "PBMCs were allowed to adhere in cell culture in the presence of phorbol ester (PMA), and after 24 h, non-adherent cells were incubated with the plasma of breast cancer patients; the expression of HPSE and HPSE2 was significantly enhanced in these cells." (PMID 30922347, 2019). "Moreover, Theodoro and colleagues observed increased levels of HPSE and HPSE2 in peripheral blood mononuclear cells (PBMCs) of breast cancer patients." (PMID 30922347, 2019).
breast carcinoma (continued). "The increased levels of Syn-1 observed in breast cancer lymphocytes, after lymphocyte exposure to the plasma of breast cancer patients and after co-culture with MCF-7 cells suggested that Syn-1 shedding could induce heparanase expression." (PMID 30922347, 2019). "Here, we found that high levels of heparanase in stage I breast cancer (with tumors smaller than 2 cm and without lymph node involvement) correlates with a 4.5-fold increased risk of disease recurrence." (PMID 29464068, 2018). "In the present study we report that in breast carcinoma patients, diabetic state conferred more aggressive phenotype (manifested by increased lymph node involvement) to heparanase-positive, as compared to heparanase-negative tumors." (PMID 28038446, 2017). "As opposed to breast carcinoma but similar to colon carcinoma, the current study found a similar rates of heparanase over-expression in primary tumors and metastases." (PMID 24887057, 2014). "We first detected the expression level and methylation of CpG sites within the heparanase promoter in MCF-7 and MDA-MB-435 cells, which represents early stage human breast cancer with low invasive capacity and late stage breast cancer with high metastatic capacity, respectively." (PMID 24632672, 2014). "These include Angiotensin 1-converting enzyme gene (ACE), which has been shown to have possible mitogenic and angiogenic effects in cell line and animal models of breast cancer, and heparanase (HPR), which has been proposed as a target for the development of breast cancer directed gene therapy." (PMID 23594746, 2013). "Although not specifically under development for breast cancer, heparanase inhibitors have entered Phase II clinical trials, with the sulfated oligosaccharide PI-88 demonstrating activity in hepatocellular carcinoma." (PMID 23300607, 2012). "Secondly, a growing body of evidence suggests that heparanase, a downstream target of EGFR/HER2, might be involved in BM from breast cancer." (PMID 22567347, 2011). "Whatever the case, it is clear that the osteolytic phenotype of aggressive human breast cancer cells involves multiple factors, including, but not limited to, heparanase, syndecan-1, and IL-8." (PMID 20200931, 2010). "Despite decades of research, much remains unknown regarding the precise role of HPSE in the establishment, early progression, and metastasis of breast cancer, largely due to the lack of robust in vivo models." (PMID 37297024, 2023). "However, robust genetic ablation animal models to investigate the role of HPSE in breast cancer have not been described." (PMID 37297024, 2023). "Furthermore, correlation of HPSE and HPSE2 in different human breast cancers was addressed to answer if both heparanases could be a useful marker to differentiate among such subtypes of cancer." (PMID 33053017, 2020). "In the present study we analyzed clinical samples of breast carcinoma derived from diabetic/non-diabetic patients, and investigated effects of heparanase on insulin signaling in breast carcinoma cell lines, as well as insulin-driven growth of breast tumor cells." (PMID 28038446, 2017). "Indeed, analysis of TCGA breast cancer RNAseq data showed that HELQ, FAM175A and HPSE were found to be differentially expressed between normal breast and tumor tissue and further analysis showed that HELQ and FAM175A expression levels are significantly decreased in basal-like tumors." (PMID 27792995, 2016). "However, the roles and regulation mechanisms of heparanase during breast cancer progression are still not fully understood." (PMID 24632672, 2014). "Combined with the previous data on HPSE-driven tumour angiogenesis, these observations suggest that a distinct upregulation of HPSE expression may not occur in MMTV-PyMT mice during mammary tumour development, but a consistent level of HPSE expression is sufficient to activate the angiogenic switch." (PMID 37297024, 2023).